LIN28B (lin-28 RNA binding posttranscriptional regulator B)
Description:
Suppressor of microRNA (miRNA) biogenesis, including that of let-7 and possibly of miR107, miR-143 and miR-200c. Binds primary let-7 transcripts (pri-let-7), including pri-let-7g and pri-let-7a-1, and sequester them in the nucleolus, away from the microprocessor complex, hence preventing their processing into mature miRNA. Does not act on pri-miR21. The repression of let-7 expression is required for normal development and contributes to maintain the pluripotent state of embryonic stem cells by preventing let-7-mediated differentiation. When overexpressed, recruits ZCCHC11/TUT4 uridylyltransferase to pre-let-7 transcripts, leading to their terminal uridylation and degradation. This activity might not be relevant in vivo, as LIN28B-mediated inhibition of let-7 miRNA maturation appears to be ZCCHC11-independent. Interaction with target pre-miRNAs occurs via an 5'-GGAG-3' motif in the pre-miRNA terminal loop. Mediates MYC-induced let-7 repression (By similarity). When overexpressed, isoform 1 stimulates growth of the breast adenocarcinoma cell line MCF-7. Isoform 2 has no effect on cell growth.
Synonyms: CSDD2; FLJ16517
Tractability: No criterion of Open Targets' tractability assessment is met for any kind of drug.
Gene: Protein-coding gene on chromosome 6 (104,936,616 to 105,083,332, forward strand). Ensembl gene ENSG00000187772.
Subcellular location: Nucleus; Nucleus, nucleolus; Cytoplasm
Subcellular location (Human Protein Atlas): Nucleoli; Nucleoplasm; Cytosol
Gene Ontology:
Molecular function: protein binding; RNA binding; sequence-specific double-stranded DNA binding; mRNA binding; nucleic acid binding; zinc ion binding
Biological process: miRNA catabolic process; negative regulation of pre-miRNA processing; negative regulation of primary miRNA processing; positive regulation of miRNA catabolic process; pre-miRNA processing; RNA 3'-end processing; RNA destabilization; post-transcriptional regulation of gene expression
Cellular component: cytoplasm; cytosol; nucleolus; nucleoplasm; nucleus
Genetic constraint (gnomAD): Loss-of-function variants: 3 observed, 18.86 expected, observed/expected ratio (o/e) 0.16, 90% interval 0.071 to 0.41. The upper end of that interval is the gene's LOEUF score, 0.41, which puts it in group 1 of 6, group 1 being the genes least tolerant of losing a copy. Missense variants: 184 observed, 232.4 expected, observed/expected ratio (o/e) 0.79, 90% interval 0.7 to 0.89. Synonymous variants: 87 observed, 85.05 expected, observed/expected ratio (o/e) 1.02, 90% interval 0.86 to 1.22.
Homologues: Orthologues: chimpanzee LIN28B (99% identical), macaque LIN28B (97% identical), pig LIN28B (93% identical), rabbit LIN28B (91% identical), dog LIN28B (88% identical), guinea pig LIN28B (88% identical), mouse Lin28b (86% identical), rat Lin28b (84% identical), tropical clawed frog lin28b (79% identical), zebrafish lin28b (56% identical), Drosophila melanogaster lin-28 (31% identical), Caenorhabditis elegans cey-4 (21% identical), and 2 more. Paralogues in human: LIN28A (54% identical), YBX1 (34% identical), YBX2 (27% identical), YBX3 (27% identical).
Diseases named in the same sentence as LIN28B in open-access papers:
LIN28B is named in the same sentence as 128 diseases in open-access papers, as found by Europe PMC text mining. Sharing a sentence is not in itself a finding about the gene and the disease. The quoted sentences say what the papers report.
neuroblastoma (58 papers, 2009 to 2025). Neuroblastoma (NB) is the most common solid, extracranial childhood tumor. "LIN28B plays a pivotal role in neuroblastoma development, being overexpressed in a subset of high‐risk patients with widespread metastases." (PMID 40679030, 2025). "LIN28B is linked with cancer stemness and, due to genomic amplification, it is occasionally found overexpressed in a subset of high-risk patients with neuroblastoma." (PMID 38338881, 2024). "The RNA-binding protein LIN28B, identified as an independent risk factor in high-risk neuroblastoma patients, is implicated in adverse treatment outcomes linked to metastasis and chemoresistance." (PMID 38338881, 2024). "They reported that LIN28B is genomically altered and overexpressed in high-risk neuroblastoma and it’s correlated with adverse clinical outcome." (PMID 37274289, 2023). "The lncRNA ADAMTS9-AS2 interacts with LIN28B to inhibit the association between LIN28B and pri-let-7 in neuroblastoma cell lines." (PMID 37991019, 2023). "LIN28B, a neuroblastoma susceptibility gene that is involved in disease initiation, promotes MYCN expression." (PMID 37991019, 2023). "LIN28B has been indirectly targeted through ornithine decarboxylase inhibition by Difluoromethylornithine, which has increased survival in high-risk neuroblastoma in combination with etoposide (NCT01059071)." (PMID 34064704, 2021). "LIN28B polymorphisms were associated with Wilms tumor 22 and neuroblastoma 23 susceptibility in Chinese children." (PMID 32284747, 2020). "Several studies have reported the aberrant expression of Lin28B and its association with outcomes in epithelial ovarian cancer, breast cancer, and neuroblastoma." (PMID 31762817, 2019). "Polymorphic alleles within the lin-28 homolog B (LIN28B) locus have been linked to neuroblastoma development and deregulated expression of LIN28B induces expression of MycN." (PMID 30760980, 2019). "For example, transgenic mice with targeted LIN28B overexpression in the sympathetic adrenergic lineage, hematopoietic tissues, and intestinal epithelium caused neuroblastoma, peripheral T-cell lymphoma (PTCL), and intestinal/colon adenocarcinoma, respectively." (PMID 28400788, 2017). "In the current hospital‐based case–control study, we found the LIN28B gene rs221634 A>T polymorphism was associated with neuroblastoma susceptibility in a Southern Chinese population." (PMID 27021521, 2016). "Considering the important role of LIN28B in carcinogenesis, we chose four potentially functional SNPs to investigate the association of genetic variants in LIN28B with neuroblastoma susceptibility." (PMID 27021521, 2016). "Low HACE1 and high LIN28B expression in diagnostic primary neuroblastomas are associated with worse overall survival." (PMID 34707697, 2012). "Importantly, the authors showed that the loss of Lin28B reduced the metastatic potential of the tumour cells, leading to a complete reversal of stage 4 to stage 1 of neuroblastoma." (PMID 36230562, 2022). "LIN28B is often overexpressed in high‐risk neuroblastoma tumors." (PMID 32945147, 2020). "Previous genome‐wide association study indicated that lin‐28 homolog B (LIN28B) might play an important role in the development of neuroblastoma and also contributed to its poor overall survival." (PMID 27021521, 2016). "In summary, in this study, we found that the LIN28B gene rs221634 A>T polymorphism might be associated with increased neuroblastoma risk in Southern Chinese childhood, especially for males, patients with tumour of mediastinum region, as well as patients in early clinical stages." (PMID 27021521, 2016). "Here, we describe the LIN28B/IGF2 signaling pathway as a novel mechanism that supports tumor angiogenesis in LIN28B‐dependent neuroblastoma." (PMID 40679030, 2025). "The intricate interplay between LIN28B, endothelial cells, and the extracellular matrix contributes to the development of the aggressive neuroblastoma phenotypes." (PMID 40679030, 2025).
neuroblastoma (continued). "Overall, our findings delineate the multiple roles of LIN28B in neuroblastoma metastatic progression, including its involvement in promoting matrix‐selective tumor cell migration and angiogenesis in vitro and in vivo." (PMID 40679030, 2025). "In this study, we explored the role of the oncogene LIN28B in the development of a pre‐metastatic niche in neuroblastoma." (PMID 40679030, 2025). "Our study indicates that the overexpression of LIN28B in neuroblastoma facilitates cell migration across the endothelial barrier and augment their angiogenic capacity." (PMID 40679030, 2025). "This suggested that LIN28B overexpression impaired the differentiation‐inducing activity of 13‐RA in neuroblastoma cells." (PMID 40679030, 2025). "The tetracycline‐directed (Tet‐On) gene expression system was used to generate an in vitro inducible LIN28B (iLIN28B) neuroblastoma cell model having LIN28B protein overexpressed in both subcellular fractions, cytosolic and nuclear." (PMID 40679030, 2025). "We investigated the effects of induced LIN28B (iLIN28B) expression on the adhesion affinity and interaction of neuroblastoma cells with specific extracellular matrix (ECM) proteins and examined their interplay with nearby endothelial cells." (PMID 40679030, 2025). "Here, we performed integrated transcriptomics and metabolomics analyses on neuroblastoma cells with induced LIN28B (iLIN28B) protein expression to outline a LIN28B-dependent metabolic profile." (PMID 38338881, 2024). "Through the doxycyclin-inducible cell system, we achieved different levels of LIN28B protein in vitro, thus mimicking the diversity found in human neuroblastoma specimens." (PMID 38338881, 2024). "In neuroblastoma, the overexpression of LIN28B correlates with stemness characteristics and increased proliferative and migratory capacities in tumor cells." (PMID 38338881, 2024). "Overall, our data extended the metabolic role of LIN28B in regulating glucose homeostasis in neuroblastoma cells." (PMID 38338881, 2024). "We find that the repression of LIN28B by SOX6 also occurs in tumor cell types representative of other tissues, such as SH-SY5Y neuroblastoma and HepG2 hepatoblastoma cells, where LIN28B is highly expressed." (PMID 38704454, 2024). "We found that ADAMTS9-AS2 overexpression inhibited cancer stem-like cell sphere formation capability, while LIN28B upregulation rescued the neuroblastoma stem-like properties." (PMID 37991019, 2023). "LIN28B and its downstream target PDZ‐binding kinase (PBK, also known as TOPK) are oncogenic in neuroblastoma and promote growth and self‐renewal via the LIN28B–let‐7–PBK axis." (PMID 37341142, 2023). "MYCN/IGF2BP1 feedback regulation also stimulates LIN28B expression, a strong inducer of neuroblastoma." (PMID 37246217, 2023). "Several studies provide evidence that LIN28B plays a crucial role in invasion and metastasis, particularly in malignant neuroblastoma." (PMID 37304235, 2023). "Immunoprecipitation proved that the RAN mRNA was a direct target of LIN28B, thus resulting in its upregulation and to an enhanced neuroblastoma cell growth." (PMID 37304235, 2023). "In neuroblastoma, JQ1 and the HDAC inhibitor panobinostat synergistically inhibited reducing the expression of LIN28B and N-Myc, and thus showed synergistic effects in the killing of neuroblastoma cells." (PMID 35135529, 2022). "In neuroblastoma cells, LIN28B promotes AURKA expression and increases MYCN expression by repressing let-7 miRNAs." (PMID 33194665, 2020). "Others have described let-7-independent pro-tumorigenic effects of LIN28B e.g. via protein-protein interaction with the transcription factor ZNF143 recruiting LIN28B to activate promoters of genes involved in neuroblastoma progression." (PMID 33585251, 2020).
neuroblastoma (continued). "Taken together, such studies aim to clarify various cellular mechanisms by which LIN28B shapes neuroblastoma aggression." (PMID 32923517, 2020). "In a murine xenograft model of neuroblastoma metastasis, we demonstrated that LIN28B indeed promotes metastasis." (PMID 32923517, 2020). "We went on to additionally define PBK as a direct transcriptional target of MYCN, thus linking PBK to two neuroblastoma oncogenes, LIN28B and MYCN." (PMID 32923517, 2020). "The remarkable effects of LIN28B and the other reported RBPs in neuroblastoma, as well as the great potential of our elucidated factors, endorse further study of RBPs in neuroblastoma." (PMID 32707690, 2020). "In the oncogenic context, LIN28B is overexpressed in multiple adult and pediatric malignancies, including leukemias,colon and pancreatic cancer, neuroblastoma, and Wilms tumor." (PMID 32923517, 2020). "Subsequently, we demonstrated that LIN28B promotes the proliferation of neuroblastoma cells and defined RAN GTPase and Aurora kinase A (AURKA) as novel genes regulated by LIN28." (PMID 32923517, 2020). "Mice overexpressing Lin28B develop multiple tumors, including lymphoma, neuroblastoma, colonic adenocarcinoma, Wilms' tumor, hepatoblastoma, and HCC 21-25, suggesting that Lin28B alone is sufficient to drive cancer." (PMID 31762817, 2019). "Mice with targeted expression of Lin28b to sympathetic adrenergic lineage cells also develop neuroblastoma." (PMID 30760980, 2019). "Lin28B indirect regulation of MycN expression by downregulation of Let-7 pre-miRNAs correspond well with a model that neuroblastoma is initiated by aberrant regulation of key developmental proteins." (PMID 30760980, 2019). "The LIN28B-RAN-AURKA-MYCN signaling cascade in the development of neuroblastoma provides a new insight into the molecular mechanism by which AURKA rs8173 reduced the risk of WT." (PMID 31636670, 2019). "Lin28B-mediated downregulation of Let-7 miRNAs increases MycN expression and targeted ectopic expression of Lin28B in mouse neural crest cells results in MycN-driven neuroblastoma." (PMID 30760980, 2019). "In neuroblastoma cells, LIN28B blocks neuronal differentiation and upregulates MYCN post-transcriptionally by blocking the let-7 microRNAs." (PMID 28400788, 2017). "In this regard, focal amplifications of ALK, CCND1, LIN28B, MDM2, and 19q13.42 observed in our study have been previously implicated in individual neuroblastoma studies 8–12." (PMID 28924153, 2017). "Overall, our findings provided further evidence for the important role of LIN28B gene in the tumourigenesis of neuroblastoma." (PMID 27021521, 2016). "klf4 and lin28b were strongly dependent on N-myc for their continued expression with reductions in the N-myc null NSC at a similar level to that observed in neuroblastoma, while klf2 was only weakly regulated." (PMID 19495417, 2009). "Particularly, LIN28B expression is frequently elevated in neuroblastomas and medulloblastomas." (PMID 40265419, 2025). "First we show that LIN28B and Sox6 expression is mutually exclusive in mouse and human erythropoiesis, which represents a well-defined model of development as well in several cancer cells, in particular neuroblastoma and hepatocarcinoma cell lines." (PMID 38704454, 2024). "Therefore, the role of LIN28B in neuroblastoma initiation and its correlation with MYCN expression makes it an important therapeutic target for intervention." (PMID 37274289, 2023). "LIN28B promotes neuroblastoma growth and metastasis through its regulation of the let‐7–PBK axis." (PMID 37341142, 2023). "Thus, LIN28B stimulated neuroblastoma cell proliferation by indirectly upregulating Aurora A kinase, which drives cell cycle progression." (PMID 37304235, 2023). "According to the critical role of LIN28B in tumorigenesis, it was reported to be a tumor-initiating factor and sufficient to induce cancer development in multiple contexts in vivo, including lymphoma, neuroblastoma, and liver cancer." (PMID 34837926, 2021).
neuroblastoma (continued). "However, LIN28B is dispensable in MYCN-amplified neuroblastoma cell lines, despite de-repression of let-7." (PMID 34771690, 2021). "Targeted expression of Lin28b to sympathetic adrenergic lineage cells gives rise to neuroblastoma." (PMID 33585251, 2020). "This suggests that Lin28B-Ran-Aurora A kinase signaling can drive neuroblastoma tumorigenesis and that this pathway could be used as a therapeutic target." (PMID 30760980, 2019). "Moreover, amplification of MYCN mRNA levels in neuroblastoma can sponge Let-7, thereby rendering LIN28B dispensable for cancer progression." (PMID 31354514, 2019). "MYCN, an oncogenic driver in neuroblastoma, controls pluripotency genes including LIN28B." (PMID 30504901, 2018). "Evidence has suggested that LIN28B may function as a key prognostic predictor for patients with colon, oesophagus cancer and neuroblastoma." (PMID 26478718, 2015). "Of further notice, LIN28B, a negative regulator of the let-7 family of miRNAs targeting MYCN mRNA, was amplified in rare neuroblastoma cases and more recently transgenic mice overexpressing LIN28B in the developing sympathetic nervous tissue were shown to develop neuroblastoma." (PMID 23308108, 2013). "Since LIN28B functions through regulation of miRNA processing including that of let-7, N-Myc activation of LIN28B in neuroblastoma may contribute to maintenance of an miRNA program that enforces an aberrant pluripotent state." (PMID 19495417, 2009). "In the case of lin28b, Myc directly binds a canonical CACGTG E-box, suggesting that our findings of N-Myc regulating lin28b expression in neuroblastoma and in NSC may be mediated through N-Myc direct binding of this E-box as well." (PMID 19495417, 2009). "However, further studies are required to unravel the intricate relationships and pathways that may mediate the impact of LIN28B on neuroblastoma metabolism through its interaction with specific miRNAs." (PMID 38338881, 2024). "In agreement with this, it is reasonable to speculate that different levels of LIN28B might have a differential impact on protein translation in neuroblastoma cells and this could reflect the different metabolic phenotypes observed in response to a different ‘time’ of LIN28B induction." (PMID 38338881, 2024). "Previous studies have shown that LIN28B promotes MYCN expression by interacting with pri-let-7 to inhibit let-7 maturation, and increasing N-Myc protein levels was associated with MYCN amplification, which plays a crucial role in the tumorigenesis of neuroblastoma." (PMID 37991019, 2023). "As LIN28B has been shown to promote metastasis in two adult epithelial malignancies, esophageal and colon cancer, we speculated that it might also influence neuroblastoma metastasis." (PMID 32923517, 2020). "Notably, Lin28B overexpression is frequently observed in various cancers, such as hepatocellular carcinoma, colorectal cancer, pancreatic cancer and non-small cell lung carcinoma (NSCLC), and is associated with induction of neuroblastoma." (PMID 27821801, 2016). "Further evidence linking LIN28B to tumorigenesis derived from several previous findings that it facilitated cellular malignant transformation in vitro and transgenic overexpression was sufficient to initiate neuroblastoma and hepatoblastoma and also required for their maintenance in murine models." (PMID 26478718, 2015). "Thus, N-Myc regulates expression of klf2, klf4, lif, and lin28b in human neuroblastoma." (PMID 19495417, 2009). "Together, these data indicated that LIN28B counteracts the differentiation stimuli provided by FN, LM, and VTN to neuroblastoma cells." (PMID 40679030, 2025). "Although direct evidence of LIN28B’s involvement in rRNA processing in cancer is limited, it has been reported that LIN28B enhances ribosomal RNA biogenesis and ribosome function in MYCN-amplified neuroblastomas." (PMID 40265419, 2025).